OSM (oncostatin M)
Diseases named in the same sentence as OSM in open-access papers (continued):
Sharing a sentence is not in itself a finding about the gene and the disease.
cancer (97 papers, 2007 to 2026). A tumor composed of atypical neoplastic, often pleomorphic cells that invade other tissues. "The associations of many myokines, including OSM, with cancer have been extensively studied in various cancer types." (PMID 38539521, 2024). "Oncostatin M (OSM), a myokine and a member of the IL-6 family, has been reported to be associated with the inhibition of cancer progression, especially in breast and lung cancers." (PMID 38539521, 2024). "Increased microvesicles lead to the activation of cancer associated fibroblasts and subsequent overexpression of pro-angiogenic factors such as OSM, IL-8, IL-11, VEGF, LIF, MMP-9, and tissue-type plasminogen activator (tPA)." (PMID 37841259, 2023). "Oncostatin M (OSM) is known as a cancer-associated cytokine that is highly expressed in patients with tumors." (PMID 35723323, 2022). "The OSM-JAK-STAT pathway has been implicated in progression of several cancers, including NSCLC; treatment of NSCLC cells with filgotinib resulted in inhibition of STAT3 activation and reduced OSM receptor expression." (PMID 33521321, 2020). "Myokines, such as osteopontin and irisin, are associated with cancer development and progression in humans, and preclinical models implicate myokines, such as oncostatin M and interleukin‐6 (IL‐6), in cancer cell growth, migration, invasion, apoptosis and angiogenesis." (PMID 38887915, 2024). "Interestingly, both IL-6 and another cytokine that signals through a gp130 receptor, OSM, have been associated with cancer cachexia, due to catabolic effects these cytokines have on muscle protein." (PMID 38022653, 2023). "In addition, OSM expression and signaling is linked to invasion and metastasis in other carcinomas including prostate, cervical, ovarian, kidney, and lung." (PMID 34011405, 2021). "In non-small cell lung cancer (NSCLC), secretion of oncostatin-M (OSM), a member of the IL-6 cytokine family, by cancer-associated fibroblasts increases STAT3 activity through activation of JAK1 and is a possible mechanism of resistance to targeted therapy such as EGFR and MEK inhibitors." (PMID 33521321, 2020). "Oncostatin M (OSM) is a multifunctional cytokine that originally derived its name from its ability to inhibit the proliferation of numerous cancer cell lines." (PMID 40343765, 2025). "Here, cancer cell-derived cytokines educate myeloid cells to reciprocate by secreting oncostatin M and IL-6, which, in turn, induces cancer-stem cell (CSC) properties in the malignant cells." (PMID 38571887, 2024). "As a member of the interleukin-6 cytokine family, Oncostatin M (OSM) plays a significant role in inflammation, autoimmune and cancer." (PMID 38903525, 2024). "A wide variety of cytokines, many of which have been implicated in cancer pathogenesis, are known to signal through receptors that include gp130, such as IL-6, IL-11, LIF, and OSM." (PMID 38022653, 2023). "Further analysis of genes dysregulated in cancer associated neutrophils revealed that TNF-α, Oncostatin M (OSM), IL-1β and IL-6 cytokines are expressed in the neutrophils with corresponding expression of their receptors in CTCs." (PMID 37006265, 2023). "IL-6 and oncostatin M have been found to directly stimulate enhanced invasion of cancer cells, stimulate the promotion of cell cycle, enhance resistance to chemotherapy, and cause epithelial-to-mesenchymal transition (EMT)." (PMID 37322531, 2023). "In this review, we outline the role OSM plays in a variety of inflammatory diseases, including cancer, and outline the previous and current strategies for developing an inhibitor for OSM signaling." (PMID 37841259, 2023). "Mechanistically, LLNLR-299G3.1 bound to cancer-associated RNA binding proteins and regulated the expression of cancer-related genes, including OSM, TNFRSF4, HRH3, and SSTR3." (PMID 37415734, 2023).
cancer (continued). "We showed that two members of the IL-6 family, LIF and OSM, induce JunB upregulation in microglia, a finding that was previously reported with respect to LIF-treated human carcinoma cells and to OSM-treated primary chondrocytes." (PMID 37894348, 2023). "OSM was first described as an antitumoral cytokine, owing to its antiproliferative effect in melanoma and other cancer cells." (PMID 35192545, 2022). "OSMR was consistently expressed mainly in epithelial/cancer cell populations, whereas the ligand OSM was specifically expressed in macrophages." (PMID 36551576, 2022). "Due to its multifaceted activities in various cancer entities, OSM is currently considered a novel therapeutic target, and a number of targeting antibodies and other compounds have been developed in preclinical research." (PMID 34769079, 2021). "Regarding myokines, we assessed irisin, OSM, osteonectin, IL-6, IL-15, and IL-7 on account of evidence supporting the utility of these myokines in the context of cancer prevention and control." (PMID 33555464, 2021). "The IL-6 family cytokine Oncostatin M (OSM) is involved in cell development, growth, hematopoiesis, inflammation, and cancer." (PMID 34769079, 2021). "We noticed that OSM expression levels in these cancers were approximately skewed distributions, and most cancer tissues were infiltrated in the environment with a relatively low concentration of OSM." (PMID 34702277, 2021). "Some myokines, such as decorin, IL-6, irisin, oncostatin-M, have been found to play a role in cancer modulation." (PMID 31936342, 2020). "Another study showed that oncostatin M (OSM), a cytokine that has been associated with cancer proliferation, neuronal development, and CNS inflammatory diseases, was also elevated after B. burgdorferi exposure." (PMID 32466166, 2020). "Of those modulated genes, SPP1, IL1RN, IL1A, TNFSF13B, OSM, and CSF3 had the most clinical relevance, as their high expression was associated with poor cancer patient overall survival." (PMID 31022845, 2019). "Although OSM was initially found to be antiproliferative in tumors, numerous tumorigenic roles for OSM have been reported in a variety of cancers." (PMID 31950039, 2019). "Oncostatin M (OSM), an interleukin-6-like inflammatory cytokine, is reported to play a role in a number of pathological processes including cancer." (PMID 26640324, 2015). "OSM was originally described as a novel, biological cancer therapy because of its ability to inhibit the growth of melanoma cells." (PMID 24675570, 2014). "The INTERVAL-GAP4 trial found increased serum levels of the myokines secreted protein acidic and rich in cysteine (SPARC) and oncostatin M (OSM) after 6 months of combined RT and AT, suggesting that these may play a role in exercise-induced cancer suppression." (PMID 39766184, 2024). "In this review, we will describe: i) the different roles that OSM plays within the human body regarding its function in inflammatory diseases; ii) the role of OSM in multiple cancer types; and iii) a detailed analysis of current targeted therapies designed to disrupt OSM signaling." (PMID 37841259, 2023). "Furthermore, evidence from both in vitro and in vivo studies supports the notion that oncostatin M (OSM), a cytokine belonging to the IL-6 family, possibly mediates some of the inhibitory effects of exercise against cancer evolution." (PMID 35454797, 2022). "In particular, OSM presents pleiotropic functions on cancers." (PMID 34702277, 2021). "However, the correlations between the expressions of OSM and typical growth factors across various cancer types were relatively weak, while the growth factors that regulate angiogenesis exhibited a stronger correlation with OSM." (PMID 34702277, 2021).
cancer (continued). "For the down-regulated genes, the common pathways that emerged from both cell lines include the Regulation of Tissue Factor signaling in cancer, Immune response_IL-1 signaling pathway, Expression targets of Tissue factor signaling in cancer, and Immune response_Oncostatin M signaling via MAPK." (PMID 29844388, 2018). "More specifically, myokines could be divided into those that may directly influence the TME, such as secreted protein rich in cysteine (SPARC), oncostatin M, and irisin; and those that may indirectly affect cancer evolution by enhancing the antitumor immune response, such as IL-6, IL-7, and IL-15." (PMID 35454797, 2022). "Among these, oncostatin M (OSM) critically contributes to physiological and pathological processes, including extracellular matrix remodeling, hematopoiesis, differentiation, inflammatory response, proliferation, acquisition of cancer stem cell markers, drug resistance, and metastatic phenotype." (PMID 36077744, 2022). "Meanwhile, neutrophils could potentiate cancer cell migration, invasion and dissemination by secreting immunoreactive molecules such as hepatocyte growth factor, oncostatin M, b2-integrins or neutrophil elastase, which might be another mechanism for CXCL5 promoting cancer progression." (PMID 29743818, 2018). "Epithelial cells secrete cytokines, inducing the aggregation of neutrophils, which, in turn, activate CAFs through OSM-OSMR signalling, thereby inducing the MIC phenotype of cancer cells through the TGF-β signalling pathway." (PMID 40657372, 2025). "The cytokine Oncostatin M (OSM) regulates homeostasis, wound healing, inflammation, and cancer progression." (PMID 41040379, 2025). "Beyond IL-6, other members of the IL-6 cytokine family, such as IL-11, leukemia inhibitory factor (LIF), and oncostatin M (OSM), also play critical roles in the interplay between inflammation and cancer." (PMID 39421736, 2024). "The gp130 family members, IL-11, IL-6, OSM, and LIF (upregulated in the LM) potentially impact skeletal muscle wasting by inducing the STAT3 signaling pathway in the preclinical model of cancer cachexia." (PMID 36774484, 2023). "Oncostatin M (OSM)/oncostatin M receptor (OSMR) signaling regulates the interactions among CAFs, cancer cells and immune cells, thereby reprogramming the pro-tumorigenic and pro-metastatic TME." (PMID 38235137, 2023). "The inflammatory cytokine oncostatin M (OSM), which belongs to the IL-6 superfamily, is an essential part of the secretome of hypoxic cancer cells." (PMID 36071472, 2022). "While the ligand OSM was only expressed by the myeloid cell populations, we found that the receptor OSMR was mainly expressed by fibroblasts, cancer cells, and endothelial cells." (PMID 35192545, 2022). "OSM, a member of the IL-6 family of cytokines, binds to OSMR and then can either promote or inhibit the growth of various cancer cells." (PMID 35036597, 2022). "Oncostatin M (OSM), a member of the IL-6 family, plays a significant role in inflammation, autoimmunity, and cancer, including liver tumors." (PMID 36077744, 2022). "Among them, a gradual increase from early-stage cancer to more advanced stages were strongest for APOC2 and IL8 genes followed by for SAA4 and OSM genes, whereas HIST1H1E, PF4V1, CXCL5, and IL2RA expression showed limited stage-wise upregulation." (PMID 33828156, 2021). "Oncostatin M (OSM), a member of the inflammatory gp130 cytokine family, has been contained to be involved in cancer invasion and metastasis." (PMID 33954053, 2021). "For instance, IL6 induces numerous cancer-promoting changes through STAT3, while IL27 or OSM can induce an opposing effect through the related signal transducer STAT1, also activated as part of the JAK/STAT pathway." (PMID 34834425, 2021). "STAT3, highly active in more than 50% of BCs, has been described as a key signalling orchestrator of many of the cancer-promoting effects exerted by IL6, but also IL11, LIF and OSM." (PMID 34834425, 2021).
cancer (continued). "Proteomic analysis of the content of these exosomes identified several established cancer- related proteins (i.e., IL-6, IL-8, ICAM-1, CCl2, and OSM)." (PMID 31803630, 2019). "Inhibition of OSM and/or OSMR has demonstrated antitumor effects and has recently been receiving increased attention as a possible cancer therapy." (PMID 29898744, 2018). "The immunological role of IL11 + CAF in cancer is not clear, but highly expressed genes, including IL-6 cytokine family (IL6, IL11, OSM) are associated with immunotherapy resistance." (PMID 39757146, 2025). "Oncostatin M (OSM), a pleiotropic cytokine and a member of the glycoprotein 130 (Gp130) family cytokines, plays a significant role in inflammation, autoimmunity, and cancers." (PMID 39935606, 2025). "In human cancer and primary cells, sgp130Fc inhibited IL6, IL11, OSM and CT1 cis-signalling." (PMID 38338642, 2024). "Three pro-inflammatory cytokines (IL-1β, IL-1α, TARC for adolescents with cancer and IL-1β, I-309, oncostatin-M for adolescents without cancer) demonstrated significantly higher levels in FF of adolescents compared to oocyte donors." (PMID 39211054, 2024). "OSM-OSMR interactions could be blocked by antibody-based inhibition, a strategy that has had a major impact on cancer, which makes them a promising candidate for therapeutic targeting." (PMID 35192545, 2022). "Normally, neutrophils do not secrete oncostatin M. However, it was found that on interaction with cancer cells, oncostatin M becomes highly expressed in TANs." (PMID 36358879, 2022). "While therapies targeting IL6-like cytokines such as IL11, OSM and CNTF are at different stages of development for the treatment of a range of diseases, only the IL11R-targeted agent BMTP-11 is being developed for its potential use in cancer treatment." (PMID 34834425, 2021). "Oncostatin M (OSM) is a member of IL-6 family cytokines with diverse activities, and it can stimulate angiogenesis by enhancing FGF-2 expression and can in vitro induce mesenchymal- and cancer stem cell-like phenotypes in cancer cells." (PMID 32422991, 2020). "Neutrophils in their normal state do not secrete oncostatin M however, upon interaction with cancer cells oncostatin M becomes highly expressed in TANs." (PMID 31430935, 2019). "On the contrary, orthologs of some cancer-related genes like oncostatin M (OSM) or leukemia inhibitory factor (LIF) have not yet been identified in zebrafish." (PMID 28894696, 2017). "Myocines produced by active muscles like oncostatin M, irisin, and SPARC can directly downregulate cancer growth by impacting cell proliferation, stemness, apoptosis, drug resistance, metabolic remodeling, and the epithelial–mesenchymal tissue transformation of cancer cells." (PMID 37958310, 2023). "Both ING4 and OSM exert a negative effect on cancer cells rather than normal cells." (PMID 35075768, 2022). "Human and zebrafish genomes are 70% similar based on conservation of individual genes, with several cancer-associated genes found in mammals but not in the zebrafish, including BRCA1, p16 (CDKN2A), BRCA1, LIF, OSM, IL6 and PML (G.D. and J.N.B., unpublished observation)." (PMID 24973744, 2014).
infection (12 papers, 2010 to 2026). The state of being infected such as from the introduction of a foreign agent such as serum, vaccine, antigenic substance or organism. "Infection of Ad-OSM was very efficient inducing hOSM secretion, causing a transient, dose-dependent systemic elevation of the cytokine." (PMID 26671477, 2015). "Among the most significant upregulated DE genes in response to MOK023, the gene for oncostatin M (OSM) was in the top 5 at all time points post-infection." (PMID 34740333, 2021). "In our data set, not only was the OSM gene transcript increased with infection, but the oncostatin M signaling canonical pathway was also significantly associated and activated in animals with high lesion scores at 21 dpi." (PMID 30696739, 2019). "Infection with EcoHIV induced OSM gene expression and protein release in BV2 cells and microglia, but not in astrocytes." (PMID 27287400, 2016). "Since OSM may play an important role in HIV-1-associated neuropathogenesis, we further investigated whether infection with a chimeric HIV-1 (EcoHIV/NL4-3-GFP virus (EcoHIV)) induces the expression of OSM and/or its receptors (OSMR-β and gp130) in cultured microglia and astrocytes." (PMID 27287400, 2016). "The IL-6 family cytokine, oncostatin-M (OSM), also enhances the expression of CXCL5 and neutrophil influx into the lungs after infection with E. coli, likely as a result of OSM-specific STAT3 (signal transduction and activator of transcription 3) activation in lung epithelial cells." (PMID 36829255, 2023). "In the study, we showed increased circulating concentrations of 47 inflammatory proteins in patients with severe infection compared to healthy controls, with the most robust increase in the circulating concentration observed for TNFSF14, OSM, CCL23, IL-6, and HGF." (PMID 36209073, 2022). "At the peak of infection, when animals developed the most severe lesions, infected animals had higher levels of several gene transcripts involved in cellular proliferation and inflammation, including matrix metalloproteinase-7 (MMP7), transglutaminase-2 (TGM2), and oncostatin M (OSM)." (PMID 30696739, 2019). "To test this hypothesis, we screened supernatants from infected cell cultures 24 h post-HSV1716gfp infection (MOI 3) for candidate molecules including adenosine triphosphate (ATP), HMGB1, type 1 interferon (IFN-⍺, IFN-β), interleukin 1-β (IL-1β), and oncostatin M." (PMID 29543735, 2018).
cardiovascular diseases (6 papers, 2013 to 2025). "While previous studies have implicated CTRC, OSM, and MMP-10 in cardiovascular disease, our study is the first to implicate them in exacerbations of COPD." (PMID 40343765, 2025). "Oncostatin M (OSM) is an inflammatory cytokine that belongs to the interleukin-6 family and is involved in various cardiovascular diseases." (PMID 34235245, 2021). "Pleiotropic cytokine oncostatin M (OSM) is secreted by T cells, monocytes/macrophages, dendritic cells and neutrophils and is known to be tightly involved in the pathogenesis of cardiovascular disorders." (PMID 36381070, 2022). "Oncostatin M (OSM) is a secreted cytokine mainly involved in chronic inflammatory and cardiovascular diseases through binding to OSM receptor β (OSMR-β)." (PMID 28258089, 2017).
inflammation (5 papers, 2021 to 2025). Aberrant reaction of the microcirculation characterized by movement of fluid and leukocytes from the blood into extravascular tissues. "Elevated levels of CEACAM6 have been associated with chronic inflammation and could serve as a more specific marker for immune dysregulation in UC compared to serum oncostatin M. CX3CL1, as a chemokine involved in immune cell trafficking, plays a crucial role in gastrointestinal mucosal immunity." (PMID 40115777, 2025). "In conclusion, in this study we have shown that OSM expression is associated with synovial inflammation and osteophyte formation, but not with cartilage damage in an acute arthritis model." (PMID 33673583, 2021).
metabolic disease (3 papers, 2018 to 2022). A congenital disorder (due to inherited enzyme abnormality) or acquired (due to failure of a metabolically important organ) disorder resulting from an abnormal metabolic process. "Oncostatin M (OSM), a member of the interleukin 6 (IL-6) family of cytokines, plays important roles in various biological functions, including inflammatory responses and metabolic diseases." (PMID 30134804, 2018).
cardiac disease (2 papers, 2016 to 2022). "OSM receptor knock-out (KO) mice with cardiac disease have demonstrated improved survival and cardiac performance; therefore, OSM could be a target for protection from cardiovascular complications." (PMID 27918443, 2016).
kidney disease (2 papers, 2020 to 2023). "Hence, increased renal production of oncostatin M may also contribute to the enhanced FGF23 production characteristic of kidney disease." (PMID 37225713, 2023). "Oncostatin M (OSM), a member of the IL-6 family of cytokines, has important roles in renal diseases." (PMID 33051515, 2020).
bacterial infection (1 paper, 2022). "Injection of IL-1α, TNFα, OSM, IL-22 and IL-17 together in the wound edges induced delayed wound healing similar to that induced by the bacterial infection." (PMID 36275755, 2022).